IL17A (interleukin 17A)
Diseases named in the same sentence as IL17A in open-access papers (continued):
Sharing a sentence is not in itself a finding about the gene and the disease.
Constipation (5 papers, 2021 to 2025). Infrequent or difficult evacuation of feces. "Abnormal proliferation of IL-17A+ CD4+ T (Th17) cells is a core feature of constipation-related inflammation." (PMID 41050658, 2025). "We found that the concentrations of TGF-β, IL-10, and IL-21 were decreased while the levels of GM-CSF, IL-17A, IL-17F, IL-22, and IL-23 were increased in constipation EAE mice and FMT EAE mice compared to EAE mice." (PMID 34301274, 2021). "We found the reduced levels of TGF-β, IL-10, and IL-21, and the increased levels of GM-CSF, IL-17A, IL-17F, IL-22, and IL-23 in the serum of constipation EAE mice." (PMID 34301274, 2021). "Moreover, the serum levels of TGF-β, IL-10, and IL-21 were decreased while the GM-CSF, IL-17A, IL-17F, IL-22, and IL-23 were increased in the constipation EAE mice." (PMID 34301274, 2021).
diffuse large B-cell lymphoma (5 papers, 2019 to 2024). "For instance, IL-17A can directly induce tumor cell proliferation and suppress apoptosis of GC cells and diffuse large B cell lymphoma cells." (PMID 36125689, 2023). "Chemoresistance in the diffuse large B-cell lymphoma (DLBCL) can be acquired by MSC secretion of IL-6 and upregulation of IL-17A." (PMID 35236376, 2022).
discoid lupus erythematosus (5 papers, 2021 to 2024). A chronic, autoimmune skin condition that manifests with a red, scaling rash, most often found on the face, ears, and scalp; these lesions often lead to permanent scarring and dyspigmentation. "Elevated serum IL-17A levels have been noted in patients with different types of lupus, such as SLE, discoid lupus erythematosus (DLE), and subacute cutaneous lupus erythematosus (SCLE)." (PMID 39124628, 2024).
gallbladder cancer (5 papers, 2018 to 2022). "IL-17A promotes gallbladder cancer invasiveness via ERK/NF-κB signal pathway mediated epithelial-to-mesenchymal transition." (PMID 32489459, 2020). "In this study, we intend to investigate the role of IL-17A on the metastasis of gallbladder cancer (GBC) and related mechanisms." (PMID 32489459, 2020). "It was previously reported IL-17A-producing γδ T cells are capable of inducing tumor angiogenesis in human gallbladder cancer, and promote OC growth via mobilization of protumor small peritoneal macrophages in a mouse model." (PMID 31064389, 2019).
generalized anxiety disorder (5 papers, 2018 to 2026). An anxiety disorder characterized by excessive and difficult-to-control worry about a number of life situations. "For example, IL-17A and IL-23A, two proinflammatory cytokines associated with Th17 activation, have shown promise as biomarkers for generalized anxiety disorder (GAD)." (PMID 40401059, 2025).
hyperreactivity (5 papers, 2016 to 2023). "Moreover, IL-1β, IL-6 and IL-23 are known to induce IL-17A production in Th17 cells and are thereby linked to airway hyperreactivity related to obesity." (PMID 27087690, 2016).
hypertriglyceridemia (5 papers, 2013 to 2026). A laboratory test result indicating elevated triglyceride concentration in the blood. "Patients with hypertriglyceridemia displayed reduced frequencies of CCR6+IL-23R+IFN-γ+ cells, whereas normal HDL levels were associated with CCR6 expression and IL-17A production." (PMID 41300932, 2025).
intracerebral hemorrhage (5 papers, 2021 to 2024). A cerebrovascular disorder characterized by bleeding into one or both cerebral hemispheres including the basal ganglia and the cerebral cortex. "For instance, they could proliferate locally and express IL-17A and IFN-γ to aggravate lesions in spinal cord injury and secondary injury after intracerebral hemorrhage." (PMID 39427160, 2024).
iron deficiency (5 papers, 2020 to 2024). "Consistent with the observations herein, iron deficiency has been reported to reduce IL-4 and IL-17A responses." (PMID 39296289, 2024).
Lewis lung carcinoma (5 papers, 2017 to 2023). "In a murine model of Lewis lung carcinoma-derived MPE, IL-10 deficiency led to increased γδ T cell intrapleural proliferation and IL-17a production, reduced MPE volume, and longer survival that was dependent on γδ T cells." (PMID 33013860, 2020).
malignant glioma (5 papers, 2010 to 2024). A grade III or grade IV glioma arising from the central nervous system. "The sera of patients with malignant glioma have been reported to have significantly elevated levels of IL-17A, compared to those harboring a meningioma or schwannoma." (PMID 26755664, 2016). "Additionally, we will identify the in vivo role of Th17 cells using IL-17A−/− or Rag1−/− mice with malignant glioma, adoptively transferred CD4+ T cells from IL-17A−/− mice." (PMID 21060663, 2010).
Multiple Organ Failure (5 papers, 2019 to 2025). A progressive condition usually characterized by combined failure of several organs such as the lungs, liver, kidney, along with some clotting mechanisms, usually postinjury or postoperative. "In addition, leptin and IL-17A may be useful as diagnostic biomarkers to identify multiple trauma patients at risk of developing multiple organ failure in an intensive care setting." (PMID 33931112, 2021). "IL17A, IL1B, MBL, and NOD2 were also reported to be associated with mortality, and PPARG was associated with multiple organ failure in our study." (PMID 40168842, 2025). "According to the ROC curve analysis, the IL-17A concentrations at time points 0 h, 48 h and 72 h were very good diagnostic markers for the discrimination between multiple trauma patients who developed multiple organ failure and patients who did not." (PMID 33931112, 2021).
Myalgia (5 papers, 2014 to 2026). "Multivariate models identified IL-15, IL-17A, IL-12p40, MCP-1, and MIP-1α as significant correlates of fever, rash, and myalgia." (PMID 42198752, 2026).
nephrotic syndrome (5 papers, 2019 to 2024). A collection of symptoms that include severe edema, proteinuria, and hypoalbuminemia; it is indicative of renal dysfunction. "We have shown that high serum IL-17A levels were associated with poor prognosis in pMN, defined by more thromboembolic complications and more relapses of nephrotic syndrome." (PMID 35603210, 2022).
neuromyelitis optica (5 papers, 2015 to 2025). A rare inflammatory disease of the central nervous system characterized mainly by attacks of uni- or bilateral optic neuritis (ON) and acute myelitis. "Proinflammatory cytokines, such as (IL: interleukin) IL-6 and IL-17A, and complement fixation are critical in the immunopathogenesis of neuromyelitis optica spectrum disorders (NMOSD)." (PMID 38326464, 2024). "IL17A was previously studied in antibody-mediated CNS disorders, such as neuromyelitis optica." (PMID 26941012, 2016).
pericarditis (5 papers, 2011 to 2025). An inflammatory process affecting the pericardium. "Interleukin-17A levels are also elevated in patients with AF, and treatment with anti-IL-17A monoclonal antibody markedly suppressed AF development in a rat model of sterile pericarditis, concomitantly reducing atrial inflammation and fibrosis." (PMID 31921897, 2019).
salmonellosis (5 papers, 2013 to 2025). Infections with bacteria of the genus salmonella. "IL-17A is essential for the recruitment and activation of macrophages and neutrophils as first line of defense against salmonellosis." (PMID 40438105, 2025).
septic arthritis (5 papers, 2010 to 2024). "IL-17A knockout mice exhibited more severe septic arthritis lesions, increased weight loss, and higher bacterial load in kidneys, indicating a protective role of IL-17A in septic arthritis." (PMID 38410388, 2024). "RAGE-/- mice with septic arthritis had significantly lower IL-17A and higher bone mineral density (BMD) compared to the control group." (PMID 27907047, 2016). "In summary, we conclude that RAGE has a limited impact on onset and on maintenance of staphylococcal septic arthritis in mice, despite decreased IL-17A levels and lower M1- macrophage polarization as compared to wild-type counterparts." (PMID 27907047, 2016). "IL-17A would only be expressed in the bone microenvironment during times of host defence in the bone (for example, septic arthritis) or during an autoimmune joint disease (for example, RA)." (PMID 20167120, 2010).
severe combined immunodeficiency (5 papers, 2013 to 2024). Severe combined immunodeficiency (SCID) comprises a group of rare monogenic primary immunodeficiency disorders characterized by a lack of functional peripheral T lymphocytes resulting in early-onset severe respiratory infections and failure to thrive. "Katayama and colleagues transferred K/BxN serum to IL-17A−/− mice and found that the disease was significantly less severe than when the K/BxN serum was transferred into wild-type mice or mice with severe combined immunodeficiency (SCID)." (PMID 26903711, 2016).
sickle cell disease (5 papers, 2019 to 2024). Sickle cell anemias are chronic hemolytic diseases that may induce three types of acute accidents: severe anemia, severe bacterial infections, and ischemic vasoocclusive accidents (VOA) caused by sickle-shaped red blood cells obstructing small blood vessels and capillaries. "Sickle cell disease patients showed significantly higher markers of endothelial function (TNF-α, IL-6, and IL-17A) in comparison to controls (p-values < 0.001, < 0.001, and 0.006, respectively)." (PMID 39354381, 2024). "Sickle cell disease patients with more severe genotypes (SS and Sβ0) had slightly greater levels of markers of endothelial function (TNF-α, IL-6, and IL-17A) than Sβ+ patients, but the difference was not statistically significant (p-values = 0.173, 0.583, and 0.720, respectively)." (PMID 39354381, 2024).
skin aging (5 papers, 2021 to 2025). The gradual irreversible changes in structure of skin that occur as a result of the passage of time.. "Interleukin 17 (or IL-17A) has a direct relationship with the stimulation of IL-23, making them a golden IL-23/IL-17 axis in age-associated inflammation and attenuates skin aging via acetyl Zingerone treatment through IL-17A stimulation." (PMID 36820091, 2021).
systemic inflammatory response syndrome (5 papers, 2021 to 2025). SIRS is a serious condition related to systemic inflammation, organ dysfunction, and organ failure. "In addition, a previous study reported that intestinal Paneth cells produce IL-17A in an IL-23-independent fashion, which is one of the causes of systemic inflammatory response syndrome." (PMID 38007487, 2023).
Acute hepatitis (4 papers, 2013 to 2025). Acute hepatic injury resulting from inflammation typically accompanied by increased serum alanine transaminase activity. "IL-17A neutralization aggravates the development of acute hepatitis in a-galactosylceramide model directed by IL-17A+NKT cells." (PMID 34211477, 2021). "Neutralizing IL-17A with monoclonal antibodies or depletion of γδT cells significantly attenuated acute hepatitis induced by Poly I:C injection." (PMID 24069246, 2013). "Since a large percentage of γδT cells secreted IL-17A in Poly I:C-induced acute hepatitis, mice were depleted of these cells and then challenged with Poly I:C." (PMID 24069246, 2013). "To determine the protective or pathological role of IL-17A in Poly I:C-induced acute hepatitis, we neutralized IL-17A using anti-IL-17A monoclonal antibodies immediately after Poly I:C challenge." (PMID 24069246, 2013). "Our data have shown a pathological role of IL-17A and γδT cells in Poly I:C-induced acute hepatitis, which may serve as potential therapeutic target for viral hepatitis." (PMID 24069246, 2013). "Without hepatic NK cells, the attenuation of ALT level by IL-17A neutralization was almost abrogated, suggesting that NK cells are indispensable in the exacerbation of Poly I:C-induced acute hepatitis by IL-17A." (PMID 24069246, 2013).
adenomyosis (4 papers, 2022 to 2025). The growth of endometrial tissue inside the muscular wall of the uterine corpus. "IL-17A and IL-17R were expressed mainly in the glandular cells of the eutopic endometrium and adenomyosis, and the expression of both IL-17A and IL-17R was found to be stronger in adenomyosis than in endometrium." (PMID 39456936, 2024). "IL-17A and IL-17R were expressed mainly in the glandular cells, and the expression of both IL-17A and IL-17R was found to be stronger in adenomyosis than in endometrium." (PMID 39456936, 2024). "The fold change of IL-17A is significantly higher in the adenomyosis group compared to the eutopic endometrium group (fold change = 7.28, p = 0.047, n = 16)." (PMID 39456936, 2024). "The result shows that the mean intensity of DAB stain is higher in adenomyosis (3.17%) than in eutopic endometrium (1.75%), demonstrating IL-17A is expressed higher in adenomyosis than in eutopic endometrium." (PMID 39456936, 2024). "By immunohistochemical staining, CD4, IL-17A, and IL-17R proteins were detected in both eutopic endometrium and adenomyosis at the level of EMI." (PMID 39456936, 2024). "CD4, IL-17A, and IL-17R immunoreactive proteins were detected within both the eutopic endometrium and adenomyosis." (PMID 39456936, 2024). "3-Diaminobenzidine (DAB) staining revealed greater IL-17A expression in adenomyosis compared to eutopic endometrium." (PMID 39456936, 2024). "Quantitative RT-PCR showed 7.28-fold change of IL-17A and 1.99-fold change of IL-17R, and the fold change level of both IL-17A and IL-17R is significantly higher in adenomyosis (IL-17A: p = 0.047, IL-17R: p = 0.027) versus eutopic endometrium." (PMID 39456936, 2024).
allergic aspergillosis (4 papers, 2017 to 2024). "Together these data suggest that lung eosinophils express RORγt and IL-17a in mice with allergic aspergillosis." (PMID 34464425, 2021). "Importantly, we again observed expression of IL-17A by the majority of lung eosinophils elicited in the new allergic aspergillosis model." (PMID 34464425, 2021). "Finally, by RT-PCR, we determined RORγt and IL-17a gene expression in FACS- sorted lung eosinophils and CD4+ T cells from wild-type and IL-23p19-/- mice with allergic aspergillosis." (PMID 34464425, 2021).
appendicitis (4 papers, 2021 to 2024). Acute inflammation of the vermiform appendix. "In the univariate logistic regression analysis, male gender (OR 2.529 [95% CI 1.230–5.203], p = 0.01) and IL-17A (OR 0.990 [95% CI 0.980–1.000], p = 0.04) were associated with an increased risk of appendicitis." (PMID 38409170, 2024). "Interestingly, the susceptibility of humans with the functional IL-17A rs2275913 polymorphism for appendicitis has been associated with advanced inflammation." (PMID 33609379, 2021). "The aim of the present study was to evaluate how the Th1 and Th17-associated cytokines IL-1α, IL-1β, IL-2, IL-6, IL-10, IL-17A and tumor necrosis factor beta (TNF-β) are associated with the risk of complicated appendicitis in children." (PMID 38409170, 2024). "These analyses showed a disruption of local T cell responses, and increased frequencies of effector IL-17A-producing CD4+ T cells in the appendix of children with complex compared to simple appendicitis." (PMID 38239362, 2023). "Increased frequencies of IL-17A+ CD4+ T cells were observed in the epithelium of the appendix of children with complex appendicitis compared to simple appendicitis." (PMID 38239362, 2023). "Appendiceal CD4+ T cell populations in children with complex appendicitis were characterized by a decrease of molecules mediating tissue-residency and an increase of IL-17A production compared to children with simple appendicitis." (PMID 38239362, 2023). "In line with the increased differentiated phenotype, cytokine production of in particular IL-17A by CD4+ T cells was increased in children with complex compared to simple appendicitis." (PMID 38239362, 2023). "IL-17A production of epithelial CD4+ T cells derived from the appendix of children with complex compared to simple appendicitis was increased upon P/I-stimulation." (PMID 38239362, 2023). "High serum concentrations of IL-6 were associated with an increased risk of complicated appendicitis in children, whereas serum concentrations of IL-1α, IL-1β, IL-2, IL-10, IL-17A and TNF-β were not." (PMID 38409170, 2024). "This prospective cohort study aimed to evaluate the association between serum concentrations of the Th1-associated cytokines interleukin (IL)-1α, IL-1β, IL-2, IL-6, IL-10, IL-17A and tumor necrosis factor beta (TNF-β) and the risk of complicated appendicitis in children." (PMID 38409170, 2024). "Furthermore, frequencies of IL-17A+ CD4+ T cells correlated with a dysregulation of the appendiceal microbiota in children with complex appendicitis." (PMID 38239362, 2023). "negatively correlated with IL-17A+ CD4+ T cells in children with appendicitis." (PMID 38239362, 2023). "In sum, the findings presented here together with data from previous studies suggest that aberrant Th17 responses are increased in complex appendicitis and plasma levels of IL-17A and IL-6 may offer potential biomarkers that should be investigated in future studies." (PMID 38239362, 2023).
bovine tuberculosis (4 papers, 2012 to 2018). "Gene transcription studies have identified dual roles for the cytokines IL-17A and IL-22 in bovine tuberculosis, where they show potential as both predictors of vaccine success and correlates of infection." (PMID 27427303, 2016). "IL-17A and IP-10 proteins are not suitable as biomarkers for bovine tuberculosis, but the levels of PPD-B- or CE-induced IP-10 mRNA transcripts should be analyzed further for their potential to be used in the diagnosis of bTB." (PMID 29560355, 2018).
Brain atrophy (4 papers, 2016 to 2025). Partial or complete wasting (loss) of brain tissue that was once present. "A relevant study revealed that plasma levels of peripheral inflammatory markers, such as BAFF/TNFSF13B, IL-4, IL-6, IL-17A, and TNF-α, exhibited associations with patterns of brain atrophy, brain hypometabolism, and clinical measures of disease severity and functional status in bvFTD." (PMID 37762113, 2023). "Similarly, plasma biomarkers GFAP, IL-17A, and lipopolysaccharide-binding protein (LBP), as well as complement factors D and C5, showed positive correlations with brain atrophy." (PMID 40305176, 2025).
cervical tumor (4 papers, 2011 to 2025). "The level of IL-17A expression was found to be higher in cervical tumor samples, 81–100 years of age, African American patients, obese and extremely obese patients, cancer stage 1 and stage 2, and in patients with tumor grade 2 and grade 3." (PMID 38816694, 2024). "The expression of IL-17A was found to be higher in cervical tumor samples, 81–100 years of age, cancer stage 1 and stage 2, African American patients, obese and extremely obese patients, and tumor grade 2 and grade 3 patients." (PMID 38816694, 2024).
cholangiocarcinoma (4 papers, 2020 to 2026). A carcinoma that arises from the intrahepatic biliary tree (intrahepatic cholangiocarcinoma) or from the junction, or adjacent to the junction, of the right and left hepatic ducts (hilar cholangiocarcinoma). "CsESPs-stimulated human cholangiocarcinoma cells (RBE) displayed elevated proliferation ability and produced higher level of IL-17A." (PMID 42085509, 2026).
chronic bronchitis (4 papers, 2016 to 2025). A type of chronic obstructive pulmonary disease characterized by chronic inflammation in the bronchial tree that results in edema, mucus production, obstruction, and reduced airflow to and from the lung alveoli. "A more relevant role for chronic bronchitis seems to be the secretion of IL-17A from Th17 cells." (PMID 39239645, 2024).
chronic lung infection (4 papers, 2016 to 2020). "Th17 lineage cytokines (IL-17A, IL-17F, and IL-22) and chemokines (CXCL1, CXCL2, CXCL5, and CXCL8) are known to control chronic lung infection caused by mycobacteria." (PMID 33520738, 2020).